APOE (apolipoprotein E)
Diseases named in the same sentence as APOE in open-access papers (continued):
Sharing a sentence is not in itself a finding about the gene and the disease.
steatosis (continued). "Here we show that conditional deletion of hepatocyte apoE using Cre-loxP technology mimics the metabolic features of global Apoe−/− mice with enhanced steatosis." (PMID 26695075, 2015). "In a proteomic investigation of drug-induced steatosis a moderate but statistically significant up-regulation of ApoE was observed in rat liver, further documenting its prognostic value in predicting DILI." (PMID 24070255, 2013). "In accordance with elevated SREBP-1, livers of the A2bAR KO mice with normal ApoE under HFD demonstrate steatosis, with increased triglyceride (TG) and cholesterol content (respectively)." (PMID 22848385, 2012). "The apolipoprotein E-knockout mice (apoE-/-) fed standard chow or a high-fat diet exhibited a profound formation of atherosclerotic plaques, but only the animals on a high-fat diet exhibited macrovesicular steatosis changes in the liver." (PMID 38913153, 2024). "Taken together, our proteomic data strongly point to peroxisomes as an important site of trehalose activity in the liver of the apoE-/- mice model, which may be responsible for the amelioration of steatosis." (PMID 38913153, 2024). "On the contrary, the administered disaccharide exhibited beneficial effects in the livers of high fat-fed apoE -/- mice, including the reduction of macrovesicular steatosis, triglyceride deposition, and plasma content as well as the level of alanine aminotransferase (ALT)." (PMID 38913153, 2024). "In addition, serum total cholesterol (TC) and low-density lipoprotein (LDL) levels in the blood were abnormally elevated, steatosis was observed in the liver cells, and atherosclerotic lesions were observed in the aortic vessels in ApoE/NOS3−/− adult mice." (PMID 36360235, 2022). "KCs in healthy and steatosis patients highly expressed C1qa, C1qb, C1qc, and ApoE transcripts." (PMID 36304458, 2022). "Furthermore, we had detected expression level of ApoE in HDFs and found that after inducing steatosis via sodium palmitate and sodium oleate, ApoE expression in HDFs." (PMID 36457728, 2022). "Here, we experimentally demonstrate that hepatic Niemann‐Pick C1‐Like 1 (NPC1L1), a cholesterol re‐absorber from bile to the liver, can cause steatosis, an early stage of NAFLD using genetically engineered L1‐Tg mice characterized by hepatic expression of NPC1L1 under the control of ApoE promoter." (PMID 32123832, 2019). "In addition, we found that p16 overexpression could increase expression level of ApoE in HDFs after inducing steatosis." (PMID 36457728, 2022). "Therefore, the ApoE knockout may blunt the beneficial effects of exercise on TG, and cholesterol; nevertheless, exercise can still mitigate the steatosis-induced hepatic damage after the administration of a HFD." (PMID 35172845, 2022). "However, a few differences between adult wild type and ApoE−/− could be observed, because the latter ones had significantly greater steatosis." (PMID 33652838, 2021). "ApoE KO mice fed HFD showed an increase in body weight, plasma cholesterol, steatosis, and liver enzymes (ALT and AST)." (PMID 36286035, 2022). "In agreement with previous findings using the ApoE knockout and HFD model, in the present study, the levels of AST and ALT were increased; this change was accompanied by hepatic TG accumulation and steatosis." (PMID 35172845, 2022). "Lipid rapidly accumulated in the liver in APOE cKO and D374Y mice fed a chow diet, but this steatosis was not immediately apparent through histological analysis." (PMID 39196121, 2024).
steatosis (continued). "Visualization of hematoxylin and eosin (H&E) and Masson’s trichrome stained liver sections showed that ApoE−/− HFD mice developed only very mild steatosis without visible fibrosis after 12 weeks." (PMID 29456458, 2018). "Interestingly, in ApoE−/− fed with WD microvesicular steatosis was predominant, while in mice fed with MCD diet mainly macrovesicular steatosis was observed." (PMID 26263022, 2015). "Compared to wild type naive mice, naive ApoE−/− mice had a higher steatosis score with no sign of inflammation (data not shown)." (PMID 23029000, 2012). "Similarly, in ApoE−/− mice on a high-fat diet, vitisin A reduced body weight gain and lowered plasma and liver TG levels while improving liver histology by decreasing NAS scores and reducing steatosis and hepatocellular ballooning." (PMID 40003987, 2025). "H&E stained liver sections showed moderate macro-vesicular and micro-vesicular steatosis throughout the hepatic lobule with minimum hepatocellular ballooning degeneration (grade 1 ballooning), no inflammatory foci and no hepatic fibrosis in ApoE–/–HFD mice." (PMID 33291840, 2020). "APOE genotype-dependent differences in very low-density lipoprotein (VLDL) secretion, hepatic clearance of circulating lipids and immune cell activation may at least contribute to the increased risk of steatosis and steatohepatitis in non-APOE epsilon 4 carriers." (PMID 37450924, 2024).
glaucoma (49 papers, 2007 to 2026). Increased pressure in the eyeball due to obstruction of the outflow of aqueous humor. "In the microbead model of glaucoma, Lgals3 is one of the genes most strongly affected by APOE deficiency." (PMID 41306973, 2025). "We further investigated the effects of risk factors such as age, gender, and APOE genotypes (ε3/ε3, ε2-, ε4-carriers) on the outcome of glaucoma (PACG and PXG) using logistic regression analysis." (PMID 38674156, 2024). "Different APOE isoforms have been demonstrated to confer differing levels of risk associated with glaucoma." (PMID 38674156, 2024). "The statistical evidence supporting a causal association between APOE variants and glaucoma remains less robust." (PMID 38674156, 2024). "Through genotyping analysis of these polymorphisms in PACG and PXG patients and ethnically matched controls, we seek to unravel potential associations between APOE genetic variants and glaucoma subtypes within this population." (PMID 38674156, 2024). "A similar inverse effect has been noted for the APOE e2 allele which is protective in AD but a risk factor for glaucoma and AMD." (PMID 36316783, 2022). "For instance, the APOE e4 allele is the most potent genetic risk factor for the development of sporadic AD; however, the e4 allele has been shown to be protective in glaucoma and AMD." (PMID 36316783, 2022). "Regarding prognosis, it would also be interesting to investigate the involvement of the APOE alleles in glaucoma." (PMID 34943212, 2021). "OPTN and APOE, implicated in Open Angle Glaucoma, demonstrated class-specific foveal enrichment among RGCs and Müller glia, respectively." (PMID 32555229, 2020). "In summary, our results demonstrate, for the first time, that APOE ε4 association in glaucoma is strongest in the NTG subgroup and that the APOE ε4 allele is inversely associated with NTG and also with POAG overall." (PMID 32614373, 2020). "The APOE allele is involved in moderating Aβ proteolysis and clearance, and is associated with both glaucoma and AD effects on the retina." (PMID 28978942, 2017). "The aim of the present study is to evaluate the impact of APOE gene ε2/ε3/ε4 polymorphism on glaucoma risk by using meta-analysis." (PMID 24885013, 2014). "Epidemiological studies have evaluated the association between Apolipoprotein E (APOE) gene ε2/ε3/ε4 polymorphism and glaucoma susceptibility." (PMID 24885013, 2014). "Recently, a number of studies have been conducted to investigate the association of APOE gene ε2/ε3/ε4 polymorphism with glaucoma risk." (PMID 24885013, 2014). "In the present study, we systemically reviewed all available published studies and performed a meta-analysis to derive a more precise estimation of the association between APOE gene ε2/ε3/ε4 polymorphism and susceptibility to glaucoma." (PMID 24885013, 2014). "Recently, two studies assessed the association of APOE gene ε2/ε3/ε4 polymorphism with primary open angle glaucoma (POAG) by using meta-analysis." (PMID 24885013, 2014). "Previous studies pointed to a possible association between APOE alleles and glaucoma in defined populations." (PMID 23687437, 2013). "A number of case-control studies were conducted to investigate the association of apolipoprotein E (Apo E) polymorphisms with primary open angle glaucoma (POAG)." (PMID 24023758, 2013). "The ε4 allele of APOE has been shown to be significantly over expressed in AD and glaucoma patients, though the contribution remains controversial." (PMID 20565898, 2010). "The frequencies of apolipoprotein E (APOE) alleles and genotypes were examined in 230 Saudi subjects including primary open-angle glaucoma (POAG; n=60) and primary angle-closure glaucoma (PACG; n=40) patients as well as 130 control subjects." (PMID 19421411, 2009).
glaucoma (continued). "In a previous study, the APOE -219G and -491T have been shown to affect optic nerve damage and visual field loss in glaucoma, which supports the importance of APOE expression and interaction with MYOC polymorphisms in the disease pathogenesis." (PMID 19578553, 2009). "So far, no attempt has been made to study a possible association between APOE alleles and glaucoma in a Saudi population." (PMID 19421411, 2009). "Many more important gene variants have recently been associated with glaucoma risk, such as apolipoprotein E (APOE), endothelin receptor type A gene (EDNRA), IL-1α, methylenetetrahydrofolate reductase (MTHFR), and beta-adrenergic receptors." (PMID 17563722, 2007). "Conversely, the presence of the ε3 isoform and overall APOE gene expression (APOE+/+) may increase the risk of RGC death in glaucoma by promoting microglial phenotypic changes and upregulating galectin-3." (PMID 38674156, 2024). "–25 Given that microglia have also been implicated in the pathogenesis of glaucoma and that APOE is upregulated in the retina and the aqueous humor of patients with glaucoma, we hypothesized that APOE and TREM2 may have genetic associations with POAG as well." (PMID 32614373, 2020). "Also, the results of studies on the association of apolipoprotein E gene (ApoE) polymorphisms with glaucoma were heterogenic." (PMID 32824523, 2020). "Also, studies on the association of apolipoprotein E gene polymorphisms with glaucoma reported heterogenic results." (PMID 31781340, 2019). "The major risk factor for neurodegenerative diseases, including glaucoma, seems to be APOE." (PMID 25893192, 2015). "Therefore, in this study, we conducted a meta-analysis to derive a more precise estimation of the association between APOE gene ε2/ε3/ε4 polymorphism and the risk for glaucoma." (PMID 24885013, 2014). "Nineteen studies examined the association between APOE gene polymorphisms and glaucoma." (PMID 24885013, 2014). "The meta-analysis suggests that APOE gene ε4ε4 may be associated with elevated risk for primary open angle glaucoma in Asians." (PMID 24885013, 2014). "Distribution of APOE allele frequencies in glaucoma patients and matched controls." (PMID 19421411, 2009). "Besides glaucoma, the APOE ε4 allele has been identified as a genetic susceptibility factor for a variety of neurodegenerative disorders in diverse ethnic populations." (PMID 19421411, 2009). "Comparison of APOE genotypes and alleles frequencies in male and female glaucoma patients." (PMID 19421411, 2009). "Earlier studies clearly point toward a possible association between APOE alleles and glaucoma." (PMID 19421411, 2009). "Furthermore, selective targeting of ApoE in long-lived myeloid cells was shown to preserve RGCs both structurally and functionally, suggesting that ApoE acts in microglia [and possibly, border-associated macrophages (BAMs)] to promote the onset of neuroinflammation in glaucoma." (PMID 36779012, 2023). "However, more epidemiologic studies based on larger sample size, case–control design and stratified by ethnicity as well as types of glaucoma are suggested to further clarify the relationship between APOE gene ε2/ε3/ε4 polymorphism and genetic predisposition to glaucoma." (PMID 24885013, 2014). "This study investigated the association between apolipoprotein E (APOE) gene polymorphisms (rs429358 and rs7412) and primary angle-closure glaucoma (PACG) and pseudoexfoliation glaucoma (PXG) in a Saudi cohort." (PMID 38674156, 2024). "In fact, tissue-specific knockouts of APOE in retinal microglia alone have been shown to protect the RGCs against OHT-induced damage in another animal model of glaucoma." (PMID 38994978, 2024). "Further studies using animal glaucoma models are needed to understand the mechanism by which APOE promoter SNPs are involved in NTG pathogenesis." (PMID 38637538, 2024).
glaucoma (continued). "This study investigated the association between apolipoprotein E (APOE) gene variants (rs429358 and rs7412) and primary open-angle glaucoma (POAG) in Arabs of Saudi origin." (PMID 38275738, 2024). "Genetic polymorphisms in apolipoprotein E (APOE) have been implicated in various systemic diseases, age-related macular degeneration (AMD), glaucoma, and other neurodegenerative disorders." (PMID 38136930, 2023). "Here we provide an overview on the suggested mechanisms underlying differential effects of ApoE isoforms in these diseases, with a focus on common pathological events between AD and retinal diseases comprising AMD, glaucoma, and DR." (PMID 37199411, 2023). "Again, this is not a direct proof of the contribution of cholesterol metabolism to the pathological mechanisms of glaucoma since ApoE protein is known to fulfill functions in the CNS in addition to cholesterol transport." (PMID 38983043, 2023). "In particular, APOA1 and APOE have been shown to be elevated in the AH of primary open angle glaucoma patients as compared to patients with cataracts." (PMID 36362243, 2022). "Understanding the underlying mechanism by which APOE ε4 is involved in the pathogenesis of glaucoma will necessitate further study in animal glaucoma models (for instance, in APOE ε2, ε3, and ε4 humanized mice, which are commercially available)." (PMID 32614373, 2020). "Thirdly, although European ancestry represented the predominant ethnic group within this study cohort, ethnic variations in glaucoma prevalence and APOE E4 allele distribution were not addressed, limiting analysis to diverse ethnic groups." (PMID 40778276, 2025). "Animal experiments suggest that APOE gene deletion (APOE−/−) and the ε4 isoform may reduce the risk of RGC loss in glaucoma by inhibiting kainic acid receptor signaling, modulating microglial activation, and reducing galectin-3 expression." (PMID 38674156, 2024). "There are several mechanisms through which APOE could potentially play a role in the pathogenesis of glaucoma." (PMID 38674156, 2024). "This study examined whether APOE genotypes correlate with clinical parameters of glaucoma, such as IOP and cup/disc ratio in both the PACG and PXG patients." (PMID 38674156, 2024). "The ApoE ε4 allele is also associated with retinal neurodegenerative diseases however in contrast to AD, it is considered protective in AMD, likewise ApoE E2 allele, which is a protective factor for AD, has been implicated as a risk factor for AMD and glaucoma." (PMID 37199411, 2023). "Indeed, one of the most highly up-regulated molecules downstream of ApoE signaling in glaucoma was Galectin-3, a secreted carbohydrate binding lectin previously implicated in a myriad of CNS degenerations." (PMID 36779012, 2023). "Furthermore, other studies showed that some patients with glaucoma had the SNP in the promoter of apolipoprotein E (APOE)." (PMID 36552999, 2022). "GAS7 may interact with other genes implicated in glaucoma pathogenesis such as MYOC, OPTN, WDR36, CAV1, nitric oxide synthase 2 (NOS2), forkhead box C1 (FOXC1), apolipoprotein E (APOE), amyloid precursor protein (APP), and clusterin (CLU)." (PMID 32545285, 2020). "We speculate that APOE may be similarly upregulated in microglia in glaucoma, as microglial reactivity has been found to contribute to glaucoma pathogenesis." (PMID 32614373, 2020). "It has also been suggested that the APOE isoform may be related to neuronal degeneration in glaucoma." (PMID 25893192, 2015). "In our study, we examine the relationship between single nucleotide polymorphisms (SNPs) of APOE (rs449647), BDNF (rs2030324), GRIN2B (rs3764028), and HSP70-1 (rs1043618) genes and the possible occurrence risk of primary open angle glaucoma in the Polish population." (PMID 25893192, 2015). "We did not detect a significant association between APOE gene ε2/ε3/ε4 polymorphism and glaucoma in overall population (P > 0.0083)." (PMID 24885013, 2014).
glaucoma (continued). "In addition to the identified genetic loci linked to POAG, other genetic factors e.g. OPA1, Apolipoprotein E, CYP1B1, E-cahderin, OPTC have been reported to elevate the risk of retinal degeneration characteristic of glaucoma." (PMID 20565898, 2010). "Distribution of APOE genotype frequencies in glaucoma patients and matched controls." (PMID 19421411, 2009). "Its possible role in RGC metabolism, together with its documented effect on neuronal survival following ischemic and traumatic insults, has led to the hypothesis that particular APOE isoforms could be related to neuronal damage in glaucoma patients." (PMID 19578553, 2009). "Given the strong evidence for the role of APOE in AD, the role of APOE in glaucoma is still unclear and the exact mechanisms by which APOE might contribute to the risk of the development and progression of glaucoma or may be protective needs further investigation." (PMID 38275738, 2024). "What is the mechanism by which APOE ε4 may be protective in glaucoma?" (PMID 32614373, 2020). "Another protein that may influence the development of glaucoma is apolipoprotein E (APOE)." (PMID 25893192, 2015). "It has been suggested that APOE plays a role in neuronal survival following ischemia and other chemical insults and that a particular APOE isoform may be related to neuronal degeneration in glaucoma." (PMID 19421411, 2009). "There is no consensus whether APOE alleles constitute a risk factor or are protective against glaucoma." (PMID 19578553, 2009). "Another microglia-relevant gene, apolipoprotein E (APOE), has been observed to have contradictory responses/affects between glaucoma and AD." (PMID 39015474, 2024). "Methylenetetrahydrofolate reductase (MTHFR) and apolipoprotein E (APOE) are among the genes that have been investigated in relation to exfoliation and glaucoma." (PMID 23687437, 2013). "In glaucoma, overexpression of APOE is restricted to the retina and not measurable in the vitreous, demonstrating a direct link to neurons." (PMID 34943212, 2021). "However, others have discovered a conflicting relationship or a negative correlation between APOE E4 and glaucoma." (PMID 38275738, 2024).